NLRP3 (NLR family pyrin domain containing 3)
Diseases named in the same sentence as NLRP3 in open-access papers (continued):
Sharing a sentence is not in itself a finding about the gene and the disease.
Alzheimer disease (continued). "NLRP3 inflammasome inhibition prevents a wide range of diseases, including Alzheimer disease, metabolic diseases, and infectious diseases." (PMID 33995345, 2021). "Chronic cerebral hypoperfusion accelerates Alzheimer's disease by enhancing NLRP3 inflammasome, and activating caspase-1 and IL-1β in hippocampus and thalamus of mice." (PMID 33509083, 2021). "Inflammasomes are a key component of innate immunity, and the NLRP3 inflammasome is known to mediate neuroinflammation in Alzheimer’s disease." (PMID 34630044, 2021). "In Alzheimer’s disease, NLRP3 inflammasome links systemic inflammation with neuroinflammation and impairs the removal of amyloid-beta by the microglia." (PMID 34885795, 2021). "TXNIP up-regulation sustains neurodegeneration by activating NLRP3 inflammasome, and enhancing the expression of caspase-1 and IL-1β in the brains of Alzheimer's disease patients." (PMID 33509083, 2021). "It is reported that the NLRP3 inflammasome also played a vital role in central nervous system (CNS) diseases, including Alzheimer’s disease (AD) PD, and HIV-associated neurocognitive disorders." (PMID 34079796, 2021). "The role of NLRP3 inflammasomes in the formation of local insulin resistance in the modeling of Alzheimer’s disease is described for the first time." (PMID 34769018, 2021). "The presence of NLRP3 in different models such as in Alzheimer’s disease, stroke, NLRP3 knock-down or knock-out animal models was shown to enhance the neuroinflammatory response." (PMID 34506597, 2021). "The NLRP3 inflammasome is suggested to contribute to the damaging inflammation that worsens Alzheimer's disease." (PMID 33597269, 2021). "Overall, activation of the NLRP3 inflammasome aggravates the pathologies of Alzheimer's disease by inducing inflammation and tissue damage." (PMID 33534121, 2021). "Pharmacological inhibitors of NLRP3 can be a beneficial strategy for the treatment of Alzheimer's disease." (PMID 33534121, 2021). "Chronic inflammasome activation is common in early onset AD patients with NOD-, LRR-, and pyrin containing 3 (NLRP3) inflammasomes contributing to Aβ plaque and tau pathology in the context of Alzheimer’s Disease." (PMID 34831129, 2021). "Amyloid β-protein (Aβ) is reported to activate NLRP3 inflammasomes and drive pyroptosis, which is subsequently involved in the pathogenesis of neurodegenerative diseases, such as Alzheimer's disease (AD)." (PMID 35126093, 2021). "The best characterized receptor family in Alzheimer’s disease (AD) is the nucleotide-binding oligomerization domain-like receptor family, pyrin domain-containing-3 (NLRP3) inflammasome." (PMID 33805626, 2021). "The compounds like IIIM-941 can be explored further for the development of therapies against diseases such as Alzheimer’s disease and Parkinson’s disease, where hampered autophagy and NLRP3 activation play a crucial role in the pathological development." (PMID 34248643, 2021). "There are several neurodegenerative diseases such as Alzheimer’s disease (AD) and Parkinson’s disease (PD) where NLRP3 mediated chronic inflammation plays a crucial role in the pathological progression." (PMID 34248643, 2021). "Evidence of its involvement in early Alzheimer’s disease includes enhanced cerebral expression of the key NLRP3 component, active caspase-1." (PMID 34188184, 2021). "Abnormal NLRP3 inflammasome activity is indeed involved in multiple neuroinflammatory diseases, including Alzheimer’s disease (AD), multiple sclerosis (MS), as well as in brain injury and viral infections." (PMID 34683104, 2021). "Our previous study has found that intestinal bacteria in patients with Alzheimer’s disease (AD) can promote the activation of NLRP3 inflammasome and mediate neuroinflammation." (PMID 34491906, 2021). "Activation of the NLRP3 inflammasome play a key role in the pathogenesis of Alzheimer’s disease (AD)." (PMID 34381452, 2021).
Alzheimer disease (continued). "Studies have confirmed that Aβ levels can be effectively reduced by inhibiting NLRP3 or knocking out related genes, and the impairment of spatial memory ability of mice with Alzheimer’s disease also can be alleviated in this way." (PMID 33192493, 2020). "NLRP3 inflammasome has been investigated in several CNS diseases, such as traumatic spinal cord injury and Alzheimer’s disease." (PMID 32192500, 2020). "NLRP3, the most intensively studied inflammasome, has been shown to be involved in many neurological diseases in adults, such as multiple sclerosis, Alzheimer's disease and Parkinson's disease." (PMID 33123073, 2020). "Here, we reviewed the mechanisms, role, and latest developments regarding the NLRP3 inflammasome with respect to three neurodegenerative diseases: Alzheimer’s disease (AD), Parkinson’s disease (PD), and amyotrophic lateral sclerosis (ALS)." (PMID 32792920, 2020). "In this review, we will primarily discuss the role of inflammasome activation by microglia in Alzheimer's disease with a special focus on Nlrp3 inflammasome activation." (PMID 33071950, 2020). "A role for NLRP3 in diseases of the central nervous system is emerging, including Alzheimer's disease and Parkinson's disease." (PMID 32148650, 2020). "The NLRP3 (NACHT, LRR and PYD domains-containing protein 3) inflammasome is implicated in a variety of human diseases including Alzheimer’s disease (AD), prion diseases, type 2 diabetes, and numerous infectious diseases." (PMID 32824985, 2020). "In animal models of other neuroinflammatory-related conditions such as Alzheimer’s disease and stroke, knock-down or knock-out of NLRP3 has been shown to decrease neuroinflammation as well as improve functional outcomes." (PMID 32252777, 2020). "NLRP3 inflammasome activation has been confirmed in neurodegenerative diseases, including PD and Alzheimer’s disease (AD)." (PMID 32432571, 2020). "The involvement of the NLRP3 inflammasome in Alzheimer’s disease, Parkinson’s disease, multiple sclerosis, and traumatic brain injury will be presented." (PMID 31892810, 2019). "Some studies have reported that NLRP3 inflammasome is of great important in the pathogenesis of some central nervous disease such as stroke, epilepsy, Alzheimer's disease (AD), and Parkinson's disease (PD)." (PMID 31214158, 2019). "Lysophosphatidylcholine (LPC) that accumulates in multiple sclerosis and Alzheimer’s disease was shown to activate both the NLRP3 and NLRC4 inflammasomes and to result in the increased IL-1β secretion seen in these patients." (PMID 31892810, 2019). "In a mouse model of APP/PS1 mice, besides inhibiting NLRP3-dependent symptoms seen in Alzheimer’s disease, MCC950 also increased the uptake of β-amyloid plaques and ameliorated neurological outcomes by inducing their clearance." (PMID 31892810, 2019). "Recent studies demonstrated a significant contribution of NLRP3 inflammasome to the progression of Alzheimer's disease (AD), the most common neurodegenerative disease." (PMID 29786072, 2019). "Despite the study of NLRC4 and NLRP3 inflammasomes in several neurological diseases (Alzheimer’s disease, Parkinson’s disease, stroke, and multiple sclerosis), their roles in gliomas remain undefined." (PMID 31133717, 2019). "The activation of NLRP3 inflammasome was critical for IL-1β release in multiple sclerosis (MS), stroke, and Alzheimer’s disease." (PMID 31142341, 2019). "Another oligomer of amyloid, amyloid β, can induce IL-1β via NLRP3 inflammasomes in a process involving the phagocytosis of amyloid β in glial cells in patients with Alzheimer’s disease (AD) and subsequent lysosomal damage and release of cathepsin B." (PMID 31182982, 2019). "Gene ontology functional enrichment analysis for the genes significantly changed by VPA in females, demonstrated potential shared mechanism with neurodegenerative diseases such as Alzheimer’s disease and Huntington’s disease, as our Nlrp3 analysis suggest." (PMID 31652960, 2019).
Alzheimer disease (continued). "NLRP3 inflammasome which consists with the NLRP3 scaffold, the apoptotic speck-containing protein (ASC) adaptor and caspase-1, has been reported to associate with neuroinflammation in Alzheimer’s disease (AD), Huntington’s disease, and pneumococcal meningitis." (PMID 30975164, 2019). "Previous studies have shown that NLRP3 contributes to the progression of Alzheimer’s disease and PD in animal models." (PMID 30131971, 2018). "Ablation of each component of NLRP3 inflammasome protects cognitive function from age-related neuroinflammation and neurodegeneration, such as in Alzheimer’s disease." (PMID 29665808, 2018). "Several NLRP3 component proteins were also induced in the pathological tissues in Alzheimer’s disease." (PMID 29410649, 2018). "Ketone supplements demonstrate promise as potential adjunct treatments for brain injury, cancer, Angelman syndrome, for reducing inflammation by suppressing activation of the NLRP3 inflammasome, and Alzheimer’s disease." (PMID 29576959, 2018). "Of different inflammasome types, NLRP3 inflammasome has drawn most attention in that the involvement of NLRP3 is highlighted in the development in Alzheimer’s disease, Huntington’s disease, pneumococcal meningitis, and TBI." (PMID 30232232, 2018). "The NLRP3 inflammasome complex has been characterized most extensively and implicated in ALS and other neurodegenerative diseases that include Alzheimer’s disease, Parkinson’s disease, frontotemporal dementia, and Huntington’s disease." (PMID 30213953, 2018). "NOD-like receptor 3 (NLRP3) plays critical roles in the initiation of inflammasome-mediated inflammation in microglia, thus becomes an important therapeutic target of Alzheimer's disease (AD)." (PMID 29743866, 2018). "It has been reported that the NLRP3 inflammasome activation significantly leads to the synaptic plasticity deficits in the pathogenesis of Alzheimer’s disease." (PMID 30233319, 2018). "Excessive activation of the NLR family pyrin domain containing 3 (NLRP3) inflammasome is involved in many chronic inflammatory diseases, including cardiovascular and Alzheimer’s disease." (PMID 28656979, 2017). "NLRP3 inflammasome activation has been detected in a number of neurodegenerative diseases, including Alzheimer’s disease and amyotrophic lateral sclerosis." (PMID 27084336, 2016). "We have characterized their activity both in vitro and in vivo and propose that fenamate NSAIDs can be rapidly repurposed as drugs to target the NLRP3 inflammasome in inflammatory diseases such as Alzheimer's disease." (PMID 27509875, 2016). "Here the authors show instead that fenamate NSAIDs inhibit the Nlrp3 inflammasome via an effect on volume-regulated anion channel function and also repurpose these drugs for therapeutic effect in rodent models of Alzheimer disease." (PMID 27509875, 2016). "Among NLRs, NLRP3 (also termed NALP3 or cryopyrin) can sense a plethora of structurally and chemically heterogeneous PAMPs and DAMPs, including amyloid β in models of Alzheimer’s disease." (PMID 25671600, 2015). "APP/Presenilin-1 (PS1) mice, which develop symptoms similar to Alzheimer's disease, were crossed with NLRP3−/− or Casp-1−/− mice." (PMID 24834051, 2014). "In Alzheimer’s disease, amyloid-β aggregates were shown to activate NLRP3 ex vivo in primary macrophages and microglia." (PMID 24137163, 2013). "Moreover, the upregulation of NLRP3 has been widely reported in activated microglia in various neurodegenerative diseases, such as Alzheimer’s disease (AD) and multiple sclerosis (MS), suggesting a shared inflammatory mechanism." (PMID 41601638, 2026). "For example, activation of the NLRP3 inflammasome has been shown to play a key role in stimulating neuroinflammation in models of Alzheimer’s disease, pointing to a microbiota–gut–inflammasome–brain axis that is crucial for understanding these cross-communication mechanisms." (PMID 40305200, 2025).
Alzheimer disease (continued). "Similarly, Gardenia jasminoides J. Ellis extract has been shown to attenuate memory impairment in Alzheimer’s disease models by inhibiting NLRP3 activation, showcasing the therapeutic potential of herbal remedies in combatting neurodegenerative conditions." (PMID 40427569, 2025). "NLRP3 inflammasome inhibitors targeting Alzheimer’s disease." (PMID 40427569, 2025). "Among the PRRs triggering microglial reactivity, the intracellular NOD-like receptor protein 3 (NLRP3) has been shown to play essential roles in various neuropathological conditions such as Parkinson ́s disease (PD), Alzheimer ́s disease (AD), and Amyotrophic lateral sclerosis (ALS)." (PMID 41562096, 2025). "TQ could suppress the NLRP3 inflammasome pathway in the hyperlipidemia-induced cardiac damage in mice, Alzheimer’s disease, and breast cancer." (PMID 41369395, 2025). "The NLRP3 inflammasome is critical in Alzheimer’s disease (AD) pathogenesis." (PMID 40538660, 2025). "TQ could suppress the NLRP3 inflammasome pathway in hyperlipidemia-induced cardiac damage in mice, Alzheimer’s disease, and breast cancer." (PMID 41369395, 2025). "Alzheimer’s disease (AD) is a multifaceted neurodegenerative disorder driven by amyloid-β (Aβ) plaques, tau neurofibrillary tangles, and chronic neuroinflammation, with the NLRP3 inflammasome playing a central role in disease progression." (PMID 40427569, 2025). "Alzheimer's disease (AD) pathology is increasingly linked to metabolic disturbances induced by high‐fat diets (HFD), with both autophagy‐lysosomal pathway (ALP) dysfunction and activation of the NLRP3 inflammasome emerging as key pathological mechanisms." (PMID 40589337, 2025). "In Alzheimer’s disease (AD) models, for instance, PANoptosis is often triggered by pathological protein aggregates like amyloid-beta (Aβ) or tau, which typically activate the NLRP3 inflammasome, a key component of the PANoptosome." (PMID 41249794, 2025). "In neurological diseases such as Alzheimer’s disease (AD) and Parkinson’s disease (PD), including other tauopathies, the activation of the NLRP3 inflammasome is triggered by protein aggregates, such as β-amyloid plaques and tau protein fibrils (protein aggregates)." (PMID 40643515, 2025). "The activation of NLRP3 inflammasome has been demonstrated to contribute to pathology in a broad spectrum of neurological diseases, such as traumatic brain injury, spinal cord injury, Alzheimer’s disease, amyotrophic lateral sclerosis, and MS." (PMID 37702910, 2024). "Finally, in a mouse model of Alzheimer’s disease (5xFAD), OL suppresses the activation of NLRP3 inflammasomes and RAGE/HMGB1 pathways." (PMID 39456822, 2024). "All these studies suggest that the NLRP3/caspase-1 axis may be a target for the treatment of Alzheimer’s disease." (PMID 37940779, 2024). "As NLRP3 inflammasome activity has been linked to many diseases and disorders, the identification of INPP5D as a member of this pathway would have therapeutic significance in other disease fields beyond Alzheimer’s disease." (PMID 38016942, 2023). "Recent studies showed that two different NLRP3 inhibitors reversed the upregulation of glycolysis in a model of LPS-induced acute neuroinflammation and affected cerebral glucose and lipid metabolism in Alzheimer’s disease model mice." (PMID 37759588, 2023). "The NLRP3 inflammasome is involved in the neuroinflammatory pathway of Alzheimer’s disease (AD)." (PMID 37793010, 2023). "Second, we pinpoint NLRP3-activating mechanisms and known NLRP3 inhibition effects in acute (ischemia, stroke, hemorrhage), chronic (Alzheimer’s disease, Parkinson’s disease, Huntington’s disease, MS, ALS), and virus-induced (Zika, SARS-CoV-2, and others) human brain diseases." (PMID 37189617, 2023). "However, the role of melatonin in suppressing activation of the NLRP3 inflammasome in Alzheimer's disease is not well understood." (PMID 37857668, 2023).
Alzheimer disease (continued). "In fact, dysregulation of the NLRP3 inflammasome is related to the pathogenesis of numerous inflammatory disorders, such as diabetic nephropathy (DN), tumor necrosis factor receptor-associated periodic syndrome (TRAPS), OA, and Alzheimer’s disease (AD)." (PMID 38037103, 2023). "Multiple studies have demonstrated the importance of the NLRP3 inflammasome in the development of immune and inflammation-related diseases, including arthritis, Alzheimer’s disease, inflammatory bowel disease, and other autoimmune and autoinflammatory diseases." (PMID 37370025, 2023). "Experimental animal models of Alzheimer’s disease revealed that the production of NOD-like receptor pyrin domain containing 3 (NLRP3) via Toll-like receptor 4 (TLR4) and the activation of the NLRP3 inflammasome via P2X7 purine receptor are essential for induction of neural inflammation." (PMID 38983051, 2023). "NLRP3 might be the “golden” therapeutic target of inflammatory morbidities, including neurodegenerative disorders (e.g., Alzheimer’s disease [AD])." (PMID 37189617, 2023). "Activation of the NLRP3 inflammasome promotes microglia to secrete inflammatory cytokines and induce pyroptosis, leading to impaired phagocytic and clearance functions of microglia in Alzheimer's disease (AD)." (PMID 37072933, 2023). "In a mouse model of Alzheimer’s disease (AD), the fibrillar peptide amyloid beta (Aβ) can be phagocytosed by lysosomes leading to lysosomal damage and cathepsin B release, which in turn activates the NLRP3 inflammasome." (PMID 37370025, 2023). "Considering the non-negligible role of NLRP3/ASC/caspase-1 axis-mediated inflammation in Alzheimer’s disease, Alzheimer’s disease transgenic mice with selective suppression of NLRP3 inflammasome or caspase-1 expressions in the brain revealed significantly improvement cognitive functions." (PMID 36009120, 2022). "In addition to MS, the NLRP3 inflammasome has important roles in neurodegenerative diseases such as Alzheimer's disease (AD), PD, and amyotrophic lateral sclerosis (ALS)." (PMID 35694441, 2022). "Research has shown that misfolded proteins like α-synuclein and β-amyloid can activate NLRP3 inflammasomes in the microglia, which may participate in neurodegenerative disease development, such as Parkinson’s and Alzheimer’s diseases." (PMID 35399689, 2022). "In addition, we attempt to update the current knowledge of the existed natural products that target NLRP3 inflammasome for AD by searching for “inflammasome”, “Alzheimer’s disease”, and “compound/natural products/formula/extracts”." (PMID 36699095, 2022). "Moreover, EPA-PC inhibited amyloid β-protein-induced neurotoxicity by alleviating the NLR family pyrin domain-containing 3 (NLRP3) inflammasome in an Alzheimer’s disease rat model." (PMID 36355016, 2022). "Given the emerging role of NLRP3 inflammasome in the neurodegenerative process, which is shared by many pathological conditions, such as Alzheimer’s disease, Parkinson’s disease, and HD, the effort of many researchers in targeting NLRP3 or inflammasome components is quite coherent." (PMID 35955494, 2022). "Moreover, targeting NLRP3 can alleviate learning and memory deficits in an Alzheimer’s disease mice model." (PMID 35431795, 2022). "This article aims to review recent research on the interaction of autophagy, NLRP3 inflammasome, and protein aggregates in Alzheimer’s disease (AD) and Parkinson’s disease (PD), analyze the mechanism and provide theoretical references for further research in the future." (PMID 36262883, 2022). "Among the inflammasomes, the nucleotide-binding oligomerization domain-, leucine-rich repeat- and pyrin domain-containing 3 (NLRP3) inflammasome is well-characterized and contributes to many neurological diseases, such as multiple sclerosis (MS), Alzheimer's disease (AD), and ischemic stroke." (PMID 35694441, 2022).